WDR1 (WD repeat domain 1)
Description:
Induces disassembly of actin filaments in conjunction with ADF/cofilin family proteins. Enhances cofilin-mediated actin severing (By similarity). Involved in cytokinesis. Involved in chemotactic cell migration by restricting lamellipodial membrane protrusions. Involved in myocardium sarcomere organization. Required for cardiomyocyte growth and maintenance (By similarity). Involved in megakaryocyte maturation and platelet shedding. Required for the establishment of planar cell polarity (PCP) during follicular epithelium development and for cell shape changes during PCP; the function seems to implicate cooperation with CFL1 and/or DSTN/ADF. Involved in the generation/maintenance of cortical tension (By similarity). Involved in assembly and maintenance of epithelial apical cell junctions and plays a role in the organization of the perijunctional actomyosin belt.
Synonyms: AIP1; HEL-S-52; NORI-1; PFITS
Tractability: Antibody: its Gene Ontology location is reachable by antibodies, with high confidence. PROTAC: ubiquitination databases record sites on it; its protein half-life has been measured.
Target class: Reader; Epigenetic regulator; Methyl-lysine/arginine binding protein; WDR domain
Gene: Protein-coding gene on chromosome 4 (10,068,089 to 10,116,988, reverse strand). Ensembl gene ENSG00000071127.
Subcellular location: Cytoplasm; Cytoplasm, cytoskeleton; Cell projection, podosome; Cell junction
Subcellular location (Human Protein Atlas): Cell Junctions; Cytosol; Plasma membrane
Pathways (Reactome):
Hemostasis: Platelet degranulation
Gene Ontology:
Molecular function: protein binding; actin filament binding; actin severing activator activity
Biological process: apical junction assembly; maintenance of epithelial cell apical/basal polarity; regulation of actin filament depolymerization; locomotion; sarcomere organization; sensory perception of sound; cortical cytoskeleton organization; establishment of planar polarity of follicular epithelium; neutrophil mediated immunity; neutrophil migration; platelet formation
Cellular component: anchoring junction; cell junction; cell-cell junction; cytoplasm; cytosol; extracellular exosome; cortical actin cytoskeleton; extracellular region; actin cytoskeleton; cytoskeleton; glutamatergic synapse; podosome; synapse
Genetic constraint (gnomAD): Loss-of-function variants: 20 observed, 64.76 expected, observed/expected ratio (o/e) 0.31, 90% interval 0.22 to 0.45. The synonymous counts are far from expectation, so gnomAD's model fits this gene poorly and the ratio says little. Missense variants: 689 observed, 789.03 expected, observed/expected ratio (o/e) 0.87, 90% interval 0.82 to 0.93. Synonymous variants: 419 observed, 340.56 expected, observed/expected ratio (o/e) 1.23, 90% interval 1.13 to 1.33.
Homologues: Orthologues: chimpanzee WDR1 (99% identical), macaque WDR1 (97% identical), pig WDR1 (97% identical), rat Wdr1 (96% identical), mouse Wdr1 (95% identical), guinea pig WDR1 (94% identical), rabbit WDR1 (93% identical), dog WDR1 (91% identical), tropical clawed frog wdr1 (80% identical), zebrafish WDR1 (64% identical), Drosophila melanogaster flr (49% identical), Caenorhabditis elegans aipl-1 (40% identical), and 1 more.
Diseases named in the same sentence as WDR1 in open-access papers:
WDR1 is named in the same sentence as 58 diseases in open-access papers, as found by Europe PMC text mining. Sharing a sentence is not in itself a finding about the gene and the disease. The quoted sentences say what the papers report.
gout (7 papers, 2008 to 2024). A condition characterized by painful swelling of the joints, which is caused by deposition of urate crystals. "Existing research suggests that CLNK and WDR1 polymorphisms significantly contribute to gout in certain populations by affecting lipid metabolism." (PMID 39512523, 2024). "The polymorphisms in the DNAH1 gene showed the potential association with male infertility in the Chinese33,34, while the variation in the WDR1 gene was the risk factor for gout development in the Chinese population." (PMID 35618720, 2022). "The G allele of rs3756230 and the A allele of rs12498927 of WDR1 were reported to be gout risk in a study of a Han Chinese cohort." (PMID 30123371, 2018). "It cannot be excluded that the gene encoding WDR1, also known as actin interacting protein 1 (AIP1) contributed at least to a minor portion to the association signals for serum UA levels and gout." (PMID 18398472, 2008). "Specifically, WDR1 appears to affect gout development via the MAPK signaling pathway, whereas CLNK may operate through the STAT signaling pathway." (PMID 39512523, 2024). "A previous study showed that epistatic interactions between WDR1 and SLC2A9 regulated serum urate concentrations, suggesting the biological value of epistatic interactions in the pathogenesis of gout.." (PMID 32000861, 2020).
breast carcinoma (6 papers, 2016 to 2023). "Abnormal WDR1 expression has been reported to be associated with breast cancer metastasis." (PMID 33194737, 2020). "Recently, the analysis of the role of WDR1 in tumors has focused on the aberrant expression of WDR1 in several tumors, including breast cancer, thyroid neoplasia, ovarian carcinoma and glioblastoma." (PMID 36875818, 2023). "VWCE has been reported to function as a tumor suppressor in breast cancer via the induction of WDR1 expression." (PMID 38123554, 2023). "The findings of our study provide solid evidence that VWCE inhibits breast cancer proliferation and metastasis by targeting WDR1." (PMID 33194737, 2020). "In conclusion, this study found that VWCE is a potent tumor suppressor in breast cancer, and its growth inhibition is mediated in part by the expression of its downstream target gene, WDR1." (PMID 33194737, 2020). "In these studies, WDR1 was identified as an oncogene for the development of oncogenic breast cancer." (PMID 33194737, 2020). "WDR1 enhances the effect of MRTF-A-induced breast cancer cell migration by promoting the expression of EMT markers and migration markers by RhoA-MRTF." (PMID 33194737, 2020). "Compared with those of healthy donors, the s-WDR1-Ab levels were significantly higher in the 192 patients with esophageal, whereas these were not significantly higher in the samples from patients with gastric, colorectal, lung, or breast cancer." (PMID 36875818, 2023). "Moreover, in breast cancer cells, knockdown of WDR1 resulted in inhibition of cancer cell migration and invasion." (PMID 34044822, 2021). "The main hypothesis we can draw from this study is that an increased level of VWCE as a regulator of WDR1 may represent a therapeutic strategy for breast cancer; however, this attractive assumption requires further validation in animal models." (PMID 33194737, 2020). "Interestingly, our mechanical and functional data allow us to better understand the functional role of WDR1 in human breast cancer." (PMID 33194737, 2020). "Therefore, VWCE may represent a novel tumor suppressor, for which its deregulation promotes breast cancer progression via the upregulation of WDR1." (PMID 33194737, 2020). "Thus, our findings suggest that VWCE may be a novel tumor suppressor that limits breast cancer progression by regulating WDR1 expression." (PMID 33194737, 2020). "In the transwell assay, WDR1 overexpression partially reversed the suppressor role of VWCE on tumor invasion in the MDA-MB-231 and MDA-MB-453 breast cancer cell lines." (PMID 33194737, 2020). "The wound healing assay showed that the overexpression of WDR1 partially reversed the suppressive role of VWCE on tumor migration in MDA-MB-231 and MDA-MB-453 breast cancer cell lines." (PMID 33194737, 2020). "Thus, WDR1 overexpression partially reversed the tumor proliferation suppressor role of VWCE in the MDA-MB-231 and MDA-MB-453 breast cancer cell lines." (PMID 33194737, 2020). "In addition, WDR1, a direct functional target of VWCE in breast cancer, may represent an attractive therapeutic target since it can be precisely targeted with specific antibodies." (PMID 33194737, 2020).
Immunodeficiency (6 papers, 2017 to 2022). Failure of the immune system to protect the body adequately from infection, due to the absence or insufficiency of some component process or substance. "Chromosome 6: the actin regulating gene WD repeat domain 1 is downregulated in lactating mammary gland of cattle and its mutation leads to autoinflammatory periodic fever, immunodeficiency, and thrombocytopenia in humans." (PMID 32777913, 2021). "Homozygous missense L153F/L293F mutation in the actin regulatory gene WDR1 causes a new AID in humans, with periodic fevers, immunodeficiency, and intermittent thrombocytopenia (PFIT)." (PMID 36253853, 2022).
hepatocellular carcinoma (4 papers, 2016 to 2024). A malignant tumor that arises from hepatocytes. "WDR1 expression has been shown to be upregulated in the highly metastatic gallbladder cancer cell line (GBC-SD18H) and to be involved in the metastasis and poor prognosis of patients with hepatocellular carcinoma." (PMID 36875818, 2023). "We also examined WDR1 distributions in the non-polarized, hepatoma-derived Clone 9 cells for ease of visualization and manipulation." (PMID 30158666, 2018).
ovarian carcinoma (4 papers, 2017 to 2023). A malignant neoplasm originating from the surface ovarian epithelium. "PHB, SRC, talin-1, tubulins and WDR1 are related to development of ovarian cancer resistance to paclitaxel and cis-platin." (PMID 29344361, 2018). "Published proteomics and molecular biology studies suggest up-regulation of ACTN4, CRKL, GELS, HSPA8, talin-1, tubulins and WDR1 in ovarian cancer." (PMID 29344361, 2018). "The conclusion of the orbitrap assays was that WDR1 protein was significantly more abundant in interstitial fluid from ovarian carcinomas versus controls." (PMID 28265552, 2017). "Levels of six candidate proteins (CEACAM5, FREM2, MUC5AC, TFF3, PYCARD, and WDR1) were further monitored in individual tumor lysates from ovarian carcinomas using MIDAS, WB, and/or SRM." (PMID 28265552, 2017).
pancreatic cancer (4 papers, 2020 to 2025). "By data mining the TCGA cohort and GTEx portal, we found that the mRNA expression level of WDR1 in pancreatic cancer (n = 179) was significantly higher than that in normal pancreas tissues (n = 175), suggesting the overexpression profiles of WDR1 in PDAC." (PMID 32601462, 2020). "Overall, our results highlight the potential involvement of HSCs, specifically the upregulation of WDR1 and the secretion of cytokines like IL1, in the process of liver metastasis in pancreatic cancer." (PMID 38291031, 2024).
Thrombocytopenia (4 papers, 2016 to 2022). A reduction in the number of circulating thrombocytes. "For WDR1, it has been previously shown that defective expression of the WDR1 gene predisposes someone to autoinflammatory disease and thrombocytopenia, which are mainly manifested by abnormal neutrophil behavior." (PMID 35371070, 2022). "Mice and humans deficient for the WDR1 gene present with a distinct IL-1 independent, but IL-18 dependent autoinflammatory phenotype and thrombocytopenia." (PMID 31456795, 2019). "Subsequently, homozygous missense mutations in WDR1 were identified in two siblings who presented with autoinflammatory recurrent fevers, thrombocytopenia, and immunodeficiency." (PMID 31456795, 2019). "Wdr1-hypomorphic mice exhibit spontaneous autoinflammatory disease and thrombocytopenia." (PMID 27627652, 2016).
glioma (3 papers, 2023 to 2025). A benign or malignant brain and spinal cord tumor that arises from glial cells (astrocytes, oligodendrocytes, ependymal cells). "Overexpression of WD repeat domain 1 promotes the proliferation of patient-derived glioma cells, indicating a synergistic effect with MYH9." (PMID 39988672, 2025). "GA-amide promotes the formation of a protein complex involving WD repeat domain 1 (WDR1) and cofilin, leading to the inhibition of migration and tumor-sphere formation involving tumor cells and glioma stem cells." (PMID 38275375, 2023). "Additionally, a 2023 study reported that gambogic amide forms a complex with WD repeat domain 1, Cofilin, and MYH9, inhibiting the invasion of patient-derived glioma cells by disrupting the cytoskeleton." (PMID 39988672, 2025). "Through direct interaction with WDR1, GA-amide promoted the formation of a complex involving WDR1, MYH9 and Cofilin, which accelerate the depolymerization of F-actin to inhibit the invasion of patient-derived glioma cells (PDCs) and induce PDC apoptosis via the mitochondrial apoptotic pathway." (PMID 37935665, 2023).
lazy leukocyte syndrome (3 papers, 2021 to 2024). "This disease was previously known as “lazy leukocyte syndrome” and is a rare inherited immunologic disorder caused by mutations in the WD repeat-containing protein 1 (WDR1) gene on chromosome 4p16.1." (PMID 38250061, 2023). "Given that WDR1 gene mutations lead to lazy leukocyte syndrome, lower WDR1 levels in neutrophils from CAP patients may impede neutrophilic responses, thereby lengthening TCS." (PMID 39493755, 2024). "Interestingly, WDR1 gene mutations affect neutrophil morphology, motility and function, causing a novel primary immunodeficiency termed the lazy leukocyte syndrome." (PMID 39493755, 2024).
primary immunodeficiencies (3 papers, 2017 to 2024). "Impaired actin dynamics as a result of WDR1 deficiency have been causally linked to primary immunodeficiencies and autoinflammatory phenotypes." (PMID 35154085, 2021). "Thus, genetic defects in WAS and WDR1 are clear examples of human syndromic primary immunodeficiencies with excessive inflammasome activation linked to dysregulation of the actin cytoskeleton, albeit with different pathogenetic mechanisms." (PMID 29146903, 2017).
cardiac hypertrophy (2 papers, 2020 to 2023). "WDR1 is involved in myocardium sarcomere organisation, and its deletion in mice models leads to cardiac hypertrophy, electrocardiogram abnormalities, and early death." (PMID 38003397, 2023). "One such miRNA is miR-200a-3p, which directly targets both WDR1 and PTEN and acts as a positive modulator of cardiac hypertrophy." (PMID 38003397, 2023). "MiR-200a-3p accelerated cardiac hypertrophy by directly modulating WDR1 and simultaneously regulating PTEN/PI3K/AKT/CREB/WDR1 pathway, while the miR302-367 cluster was found to impair autophagy to worsen cardiac hypertrophy through silencing PTEN and consequently activating PI3K/AKT/mTOR pathway." (PMID 33195446, 2020).
colorectal cancer (2 papers, 2016 to 2022). A primary or metastatic malignant neoplasm that affects the colon or rectum. "Significant increases (> 0.6) in the AUC for BRAT1-Ab vs. esophageal squamous cell carcinoma (ESCC), gastric cancer, and colorectal cancer suggested that BRAT1-Ab exhibited better predictive potential for GI cancers than WDR1-Ab." (PMID 35656505, 2022).
Macrothrombocytopenia (2 papers, 2013 to 2017). "When WDR1 loses its function, it leads to embryonic lethality, macrothrombocytopenia and autoinflammatory disease." (PMID 28719625, 2017).
pancreatitis (2 papers, 2015 to 2025). Inflammation of the pancreas. "The DEGs, including Cdc6, Mcm6, Msh6 and Wdr1 are closely associated with the regulation of caerulein-induced pancreatitis." (PMID 25975747, 2015). "Five key factors were identified: Wdr1, Naa10p, Ptpn12, Upf1, and Ralb, all significantly upregulated in pancreatitis mice." (PMID 40557397, 2025). "Msh6 and Wdr1 may be involved in the regulation of pancreatitis through DNA mismatch repair and acinar cells, respectively." (PMID 25975747, 2015). "Thus, Wdr1 is hypothesized to be involved in the regulation of pancreatitis through acinar cells." (PMID 25975747, 2015).
transient ischemic attack (2 papers, 2022 to 2023). A brief attack (from a few minutes to an hour) of cerebral dysfunction of vascular origin, with no persistent neurological deficit. "Using serological antigen identification by cDNA expression cloning (SEREX) and western blot, we screened and detected the antigens BRCA1-Associated ATM Activator 1 (BRAT1) and WD Repeat Domain 1 (WDR1) in the sera of patients with transient ischemic attacks (TIA)." (PMID 35656505, 2022). "The presence of autoantibodies against WDR1 has been found in the sera of patients who have suffered a transient ischemic attack using SEREX screening." (PMID 36875818, 2023). "WDR1 was identified using large-scale SEREX screening with the sera of patients with a transient ischemic attack as an antigen recognized by serum IgG antibodies." (PMID 36875818, 2023).
aphthous stomatitis (1 paper, 2020). "Patients with WDR1 deficiency can suffer from severe aphthous stomatitis* leading to oral stenosis, and from candidiasis." (PMID 32625202, 2020).
artery thrombosis (1 paper, 2016). "In a FeCl3 induced carotid artery thrombosis model, vessel occlusion in Wdr1-hypomorphic mice was prolonged significantly compared to wild-type mice (9.0 ± 10.5 minutes versus 5.8 ± 12.6 minutes (p = 0.041)." (PMID 27627652, 2016).
bipolar disorder (1 paper, 2026). A disorder of the brain that causes unusual shifts in mood, energy, activity levels and the ability to carry out day-to-day tasks. "WDR1, involved in actin formation and auditory perception, has been shown to be differentially expressed in the dorsolateral prefrontal cortex of schizophrenic patients and haplotype analyses have implicated the WDR1 locus in bipolar disorder as well." (PMID 41510670, 2026).
Bladder Urothelial Carcinoma (1 paper, 2022). "For example, the editing level on two ubiquitination sites, chr1:110256304 on GSTM5 and chr4:10080600 on WDR1, were significantly different between tumor and para-tumor samples in Bladder Urothelial Carcinoma (BLCA) and Head and Neck squamous cell carcinoma (HNSC), respectively." (PMID 36064557, 2022).
endometrial cancer (1 paper, 2023). Primary or metastatic malignant neoplasm involving the endometrium (mucous membrane that lines the endometrial cavity). "The incorporation of RTN4, LAMP2, WDR1, KRT13, ALDH2 and ILF3 gave rise to a ten-marker biomarker panel, which predicted endometrial cancer with an AUC of 0.91 (0.86–0.96), and was the best performing diagnostic model." (PMID 36807337, 2023).
esophageal carcinoma (1 paper, 2023). A primary or metastatic malignant neoplasm involving the esophagus. "In conclusion, the present study demonstrated that serum anti-WDR1 antibody titers were significantly higher in patients with esophageal carcinoma than in healthy subjects." (PMID 36875818, 2023). "The results of the present study also revealed significantly high levels of WDR1 antibody in esophageal carcinoma." (PMID 36875818, 2023). "The results revealed that the s-WDR1-Ab levels in patients with esophageal carcinoma were significantly higher than those from healthy donors (P<0.001)." (PMID 36875818, 2023). "The present study found that the s-WDR1-Ab levels were significantly higher in patients with esophageal carcinoma than in healthy subjects." (PMID 36875818, 2023). "ROC analysis resulted in an area under the ROC curve (AUC) for s-WDR1-Ab of 0.648 for esophageal carcinoma." (PMID 36875818, 2023). "Therefore, the present study aimed to evaluate the serum levels of anti-WDR1 antibodies (s-WDR1-Abs) combined with serum levels of anti-CFL1 antibodies (s-CFL1-Abs) in patients with esophageal carcinoma." (PMID 36875818, 2023). "On the whole, the present study demonstrates that the combination of positive anti-WDR1 antibodies with negative anti-CFL1 antibodies in serum may be a poor prognostic factor for patients with esophageal carcinoma." (PMID 36875818, 2023). "The combination of positive anti-WDR1 antibodies with negative anti-CFL1 antibodies may be a poor prognostic factor for patients with esophageal carcinoma." (PMID 36875818, 2023).